SOX2 (SRY-box transcription factor 2)
Diseases named in the same sentence as SOX2 in open-access papers (continued):
Sharing a sentence is not in itself a finding about the gene and the disease.
colorectal cancer (continued). "However, the role of SOX2 in colorectal cancer (CRC) remains unclear." (PMID 32104175, 2020). "For instance, in colorectal carcinoma, the expression of METTL3 is elevated, resulting in higher m6A level in oncogene SOX2." (PMID 31801551, 2019). "In colorectal carcinoma, IGF2BP2 recognizes m6A in the coding sequence (CDS) regions of target gene SOX2 and prevents it degradation, contributing to colorectal cancer pathogenesis and progression." (PMID 31801551, 2019). "A recent study was particularly instructive, showing the variability of the optimal ROI to be analyzed for five different colorectal cancer stem cell markers (ALDH1, CD44v6, CD133, LGR5 and SOX2)." (PMID 29652830, 2018). "We next assessed the SOX2's effect on cell migration and invasion using an established stable SW620 colorectal cancer cells expressing shRNA-SOX2 (SW620shRNA-SOX2) using transwell migration and invasion assays (Corning Inc., USA)." (PMID 22912670, 2012). "In a previous study, we successfully knocked down SOX2 in a colorectal cancer cell line SW620, in which SOX2 is highly expressed." (PMID 22912670, 2012). "The loss of exosomal miR-200b-3p release from CAFs under hypoxic conditions potentially contributes to colorectal cancer progression by increasing the stemness potential of colorectal cancer cells via upregulation of CD133, SOX2, N-cadherin, ZEB1 and E2F3, which are direct targets of miR-200b-3p." (PMID 39928285, 2025). "Moreover, in colorectal cancer, METTL3 targets genes such as SOX2, HK2, SLC2A1, and CBX8, inducing metastasis-related processes and activating the glycolysis pathway and cellular stemness." (PMID 38966069, 2024). "For example, lncRNA LOC100507144 could contribute to colorectal cancer progression and metastasis through regulating CD44/Nanog/Sox2/miR-302/miR-21 axis." (PMID 35635595, 2022). "Interestingly, the induction of SOX2 and CSC characteristics, including CD44+ cells in colorectal cancer, were only affected by the inactivation and downregulation of PI3K/AKT following irradiation." (PMID 33445526, 2021). "Interestingly, both the knockdown and overexpression of SOX2 led to increase in CD44+ population and induction of CSC properties in colorectal cancer following irradiation." (PMID 33445526, 2021). "In this study, we aimed to identify benefits and drawbacks with DIA and mIHC in comparison with conventional IHC analyzed according to the Allred method for colorectal cancer research and clinical use, with a particular focus on the clinically relevant markers CDX2 and SOX2." (PMID 31641225, 2020). "As CSC properties have been associated with angiogenesis and vasculogenic mimicry (VM), we aimed to comprehensively investigate whether SOX2 regulates CSC properties, angiogenesis, and VM in colorectal carcinoma (CRC) and its potential mechanism in this study." (PMID 32144236, 2020). "In addition to the Sox2 reporter, we also found one recent publication in which the CSC population from colorectal cancer was identified based on their differential response to a Wnt reporter." (PMID 29609590, 2018). "In colorectal cancer, miR-200c and SOX2 also appear to regulate one another by a negative feedback loop." (PMID 28388544, 2017). "In colorectal carcinoma (CRC), METTL3 seems to havea key roleby methylating the transcripts of SOX2, a transcription factor thatenables the maintenance of an undifferentiated state in embryonicand pluripotent stem cells." (PMID 36692498, 2023). "All in all, although in vivo experiments are needed, this study reveals a novel FENDRR/Sox2 axis necessary for the CSC-like traits and chemoresistance of colorectal cancer cells, which might be a novel biomarker for colorectal cancer and chemotherapeutic efficiency." (PMID 34697986, 2021).
colorectal cancer (continued). "Moreover, an integrated analysis of the clinical and survival impact of SOX2 in colorectal cancer showed that SOX2 expression was not significantly related to clinical stage and histological grade." (PMID 34436030, 2021). "Previous studies have shown that METTL3 methylated SOX2 transcripts, subsequently recognized by the specific m6A “reader” and insulin-like growth factor 2 mRNA-binding protein 2 (IGF2BP2), to maintain SOX2 stability and promote colorectal carcinoma progression." (PMID 34858987, 2021). "Moreover, the studies have also shown that CXCL/CXCR and PI3K/AKT/STAT3 signaling pathways participate in the regulation of EMT- and cancer stem cell- associated events, and up-regulate the expression of Snail, Twist, ZEB1, Oct4, Sox2, c-Myc, Nanog and KLF4 in colorectal cancers." (PMID 28350360, 2017). "Moreover, a miR-200c-SOX2-negative feedback loop regulates stemness, growth and metastasis in colorectal cancer." (PMID 25868860, 2015). "Study also showed that LDL could enhance stemness by increasing stemness-related genes, such as Sox2, Oct4, Nanog, and Bmi1 in colorectal cancer cells, increased ROS levels that can further activate MAPK pathways, and stimulated intestinal inflammation and colorectal cancer." (PMID 35251975, 2022). "Digital image analysis (DIA) of multiplex fluorescence-based immunohistochemistry and visual chromogenic evaluation of CDX2, SOX2, SOX9, E-cadherin, and β-catenin in colorectal cancer are comparable, recognizing prognostic value of CDX2 and negative correlation with SOX2." (PMID 31641225, 2020). "In addition, MG cells expressed surface markers of colorectal cancer stem cells (ALDH1A1, CD24, POU5F1, SOX2, and SOX9) to a greater degree compared with non-MG cells." (PMID 31936744, 2020). "To explore the role of Sox2 and other iPS factors in cancer, we ectopically expressed these factors in HCT116 human colorectal cancer cells and found that Sox2, but not Nanog, Lin28 or Oct4, induced severe vacuole formation in the cytoplasm, which is an important marker of macroautophagy." (PMID 23451179, 2013).
gastric cancer (156 papers, 2008 to 2026). A primary or metastatic malignant neoplasm involving the stomach. "Mutations of several genes encoding for proteins involved in DNA damage response and repair were also more prevalent in gastric cancers with suppressed SOX2 mRNA expression, although the frequency of mutations in each individual gene was low." (PMID 40149431, 2025). "In contrast, almost all other common mutations of gastric cancer were more prevalent in the group with SOX2 suppression." (PMID 40149431, 2025). "SOX2 is a regulator of foregut development and has been associated with both tumor-promoting and tumor-curtailing effects in gastric cancer." (PMID 39768557, 2024). "Tissue of gastric cancer showed high expression levels of SOX2, and SOX2 overexpression is linked to a poor prognosis." (PMID 38256203, 2024). "Expression of OCT4, SOX2, and Nanog, either alone or in combination was found positively associated with phenotypes of advanced gastric cancer and worse prognosis, while that of KLF4 was inversely correlated." (PMID 36661504, 2022). "The expression of pluripotency factors including Nanog, OCT4, and SOX2, and their association with prognosis, are also known in gastric cancer." (PMID 36661504, 2022). "Aberrant SOX2 expression has been reported to be associated with various types of cancer, especially gastric cancer." (PMID 30733645, 2019). "Univariate analysis showed that expression of Sox2 was the only factor associated with prognosis for overall patients with gastric cancer at Stages I and II." (PMID 28046028, 2017). "Our results indicate that predictive value of Sox2 in gastric cancer is associated with cardiac cancer location and with early cancer stages (I and II)." (PMID 28046028, 2017). "A few studies have revealed an association of SOX2 expression with a favorable prognosis in non-small cell lung cancer, gastric cancer and renal cell carcinoma." (PMID 26370982, 2015). "Numerous gain and loss of function studies in several cancer types (gastric cancer, ovarian cancer and hepatocellular carcinoma) reinforced the link between SOX2 and cellular invasion and migration." (PMID 25114775, 2014). "We further investigated the SOX2 methylation status in human cultured and primary gastric cancer cells to clarify the mechanisms underlying the loss of SOX2 expression in gastric cancers." (PMID 18268498, 2008). "The group with SOX2 suppression had higher rates of mutations in many gastric cancer-associated genes such as epigenetic modifiers ARID1A, KMT2D, KMT2C, and KMT2B, as well as higher rates of mutations in genes encoding for receptor tyrosine kinases ERBB4 and FGFR1." (PMID 40149431, 2025). "However, other studies have shown the contrary, indicating that the relevance of SOX2 in gastric cancer needs further clarification, namely its association with the CSC phenotype." (PMID 32093282, 2020). "CSC in gastric cancers had been reported recently and SOX2 had been implicated in maintaining stem-like properties of gastric cancer cells and enhanced chemoresistance to cisplatin or Adriamycin, possibly via upregulation of ABC drug transporters (MRP2 and MDR1)." (PMID 30517668, 2020). "However, another study found that compared with SOX2-positive gastric cancer, decreased SOX2 expression in gastric cancer was associated with an increased extent of tumor invasion, higher rates of lymph node metastasis and shorter survival." (PMID 30733645, 2019). "We failed to determine whether SOX2 has a functional role in tumorigenesis; however, our findings indicate that inflammation-associated SOX2 expression can be a useful marker for detecting an early stage of gastric cancer." (PMID 30700829, 2019). "SOX2 is associated with pathological stage and clinical outcome in gastric cancer." (PMID 30186173, 2018). "Moreover some studies of gastric cancer indicate that elevated SOX2 levels are linked to reduced lymph node and distant metastases." (PMID 28388544, 2017).
gastric cancer (continued). "However, the association of ALDH1 and Sox2 expression with pathological parameters and patient survival in gastric cancer remains controversial." (PMID 28046028, 2017). "High SOX2 in gastric cancer has been reported to be associated with longer patient survival." (PMID 28388544, 2017). "Some studies found that Sox2 high expression might be associated with invasion of gastric cancer and poor survival outcomes." (PMID 27557490, 2016). "Finally, we unraveled the heterogeneity of SOX2 locus and chromosome 3 copy number in gastric cancer, demonstrating an association between increased copy number and SOX2 protein expression." (PMID 25300947, 2014). "Taken together, our findings may lead to new diagnostic and therapeutic approaches for gastric cancer, and provide new insights into the transcriptional regulation of SOX2." (PMID 21304604, 2011). "We performed cDNA microarray analysis to identify the downstream target genes of SOX2 in gastric cancer cells, and found that many tumor-associated genes exhibited significant changes in expression after SOX2-overexpression (e.g., LTF, PPP2R1B, TGFBR2, SERPINE1, MMP9, HMGA1 and SOX9)." (PMID 21304604, 2011). "Next, we tried to clarify the mechanisms underlying the loss of SOX2 expression in gastric cancers." (PMID 18268498, 2008). "The proportion of pathogenic mutations in the examined WNT/APC/β-catenin pathway genes of the MSI-high subgroup of CDX2-induced, SOX2-suppressed gastric cancers was 28.6% (22 of 77 mutations), while the rest were of unknown significance, according to the evaluation in the OncoKB knowledgebase." (PMID 40149431, 2025). "However, SOX2 suppression may be permissive for a sub-set of gastric cancers with CDX2 induction to acquire mutations in epigenetic modifier genes, including ARID1A, KMT2D, KMT2C, KMT2A, and KMT2B." (PMID 40149431, 2025). "Furthermore, there exists a significant association between SOX2 expression levels and poor survival outcomes along with unfavorable prognoses for patients with gastric cancer; consequently, those with more favorable outcomes tend to display higher levels of SOX2 expression." (PMID 39976818, 2025). "Thus, the loss of SOX2 in gastric carcinomas could contribute to tumorigenesis by inducing proliferation." (PMID 37760529, 2023). "While antral stem cells expressing Lgr5, Mist1 or Sox2 may be among the gastric cancer origin cells in the setting of Apc loss, Lgr5+ cells have been implicated in more invasive types of gastric cancer, characterized by the simultaneous loss of Pten and Smad4, or by the loss of Lats1 and Lats2." (PMID 30384487, 2018). "Research suggests that elevated levels of SOX2 can inhibit distant metastasis in gastric cancer primarily by reducing lymph node involvement." (PMID 39976818, 2025). "The findings of the present study suggest that LA considerably suppresses key features of gastric cancer stemness through the Akt/Nrf2/CD44/SOX2 signaling pathways." (PMID 40864800, 2025). "Mutations in APC were also frequent in gastric cancers with CDX2 induction and SOX2 suppression (16.2% of cases), and the difference in prevalence compared with SOX2-maintained-expression cancers approached significance (Fisher’s exact test with p = 0.06)." (PMID 40149431, 2025). "The present study evaluated the levels of proteins associated with stemness after LA treatment of gastric cancer cells and revealed that LA suppresses cancer stemness through the Akt/Nrf2/CD44/SOX2 signaling axis." (PMID 40864800, 2025). "Overexpression of ATG4A has been shown to promote the epithelial‐mesenchymal transition (EMT) phenotype and stem‐like properties in gastric cancer cells, characterized by reduced E‐cadherin levels and elevated Sox‐2 expression." (PMID 40883962, 2025). "Specifically, we evaluated the potential regulatory influence of JMJD3 on the expression of key stemness markers, including OCT4, LIN28, SOX2, CD133, and CD44, which are associated with gastric cancer." (PMID 41184226, 2025).
gastric cancer (continued). "The group of gastric cancers with retained SOX2 expression belonged more often (74.5%) to the chromosome instability (CIN)-high genomic category compared with SOX2-suppressed group where CIN cancers constituted 54.6% of the group." (PMID 40149431, 2025). "On the other hand, SOX2, which is a specification transcription factor for the foregut and is normally expressed in gastric epithelia, becomes often suppressed in gastric carcinomas." (PMID 40149431, 2025). "In a study on gastric cancer, it was shown that DDIT3 can directly upregulate the transcription factor CEBPB, thereby increasing the stemness of gastric cancer cells and the expression of stem cell markers: SOX2, NANOG, OCT4, and CD133." (PMID 38710698, 2024). "It has been demonstrated that SOX2 suppresses cell migration and the invasion of gastric cancers (GCs), and its low expression, frequently seen in GCs, is strongly associated with poor outcomes for GC patients." (PMID 38334608, 2024). "SOX2 controls important signaling pathways, regulates expression, and provides new therapeutic options for a subset of gastric cancers with SOX2 dysregulation." (PMID 38883131, 2024). "Our results show that ciclopirox olamine (CPX) is able to reprogram gastric cancer cells to a stem-like phenotype via SOX2 expression, reprogram cell metabolism, and induce senescence." (PMID 37686684, 2023). "In normal gastric mucosae, SOX2 is normally expressed, but it is downregulated in gastric carcinomas." (PMID 37760529, 2023). "MALAT1 directly binds to SOX2 mRNA, which enhances its stability so that it can have a positive effect on the regulation of stemness of gastric cancer cells." (PMID 35650297, 2022). "Changes in the expression of three pluripotency factors (KLF4, Nanog, and SOX2) except OCT4 were examined in the gastric cancer cells treated with cisplatin or TRAIL for 72 h by western blotting." (PMID 36661504, 2022). "Knockdown of GRP78 expression or inhibition of GRP78 by ISL downregulated CD24, CD44, LGR5, SOX2, and Nanog in gastric cancer in our study." (PMID 35740372, 2022). "In gastric cancer, higher Sox2 expression positively correlated with doxorubicin resistance and when SOX2 was inhibited using siRNA, the ability of the spheroid formation was significantly affected." (PMID 35875180, 2022). "SOX2, in addition to being transcriptionally regulated by Gli1, is post-transcriptionally regulated in gastric cancer by AKT activation in a ubiquitin-dependent manner." (PMID 33499351, 2021). "HOXC9 has been suggested to promote the CSC phenotype in gastric cancer cells in vitro, as observed by the downregulation of CSC-associated surface markers CD44 and EpCAM, and CSC-associated markers SOX2 and OCT-4, after the knockdown of HOXC9." (PMID 33562727, 2021). "MALAT1 was shown to directly bind to and stabilize Sox2 mRNA, which led to the increase of stemness and chemo-and radioresistance of gastric cancer cells." (PMID 33482814, 2021). "In gastric adenocarcinoma, RAC1 overexpression promoted the CSC phenotype, chemotherapy resistance, and expression of SOX2 in spheroids of gastric cancer cells." (PMID 34771704, 2021). "Although it is still controversial, it has been suggested that the increased expression of SOX2 results in a poorer prognosis in gastric cancer." (PMID 33562727, 2021). "Conversely, in gastric cancer cells CMIP induces the activity of SOX2, upregulates MDM2 and MAPK transcription." (PMID 33917766, 2021). "As such, Helicobacter pylori infections was shown to influence SOX2 expression in gastric cancer, where SOX2 has been described as a trans-activator of PTEN, thus inhibiting PI3K/AKT-driven cell cycle progression and anti-apoptosis effects." (PMID 31477842, 2020). "In this study, we highlight the relevance of SOX2 in the behavior of gastric cancer but there are other molecular players, such as the recently identified USF1 whose interaction with the CSC phenotype needs to be addressed." (PMID 32093282, 2020).